OLIG1 (oligodendrocyte transcription factor 1)
Diseases named in the same sentence as OLIG1 in open-access papers (continued):
Sharing a sentence is not in itself a finding about the gene and the disease.
Obesity (1 paper, 2015). Accumulation of substantial excess body fat. "LACA mice can provide advantages against C57BL/6 when studying genes such as Zic1 or Olig1 or their associated pathways, which can be explored clinically as alternative strategies for the treatment of obesity and associated co-morbidities." (PMID 26010905, 2015). "Oligodendrocyte transcription factor 1 (Olig1) whose role in obesity or adipose tissue is not well-studied, seems to play an important role in LACA mouse BAT." (PMID 26010905, 2015).
oligodendroglial tumor (1 paper, 2005). Oligodendrogliomas are cerebral tumors that are differentiated from other gliomas on the basis of their unique genetic characteristics and better response to chemotherapy. "Id4 expression is present primarily in neoplastic astrocytes in both oligodendroglial tumors and GBM, which is in contrast to the expression patterns of OLIG1 and OLIG2, two survival-associated genes originally identified in GBM tumors." (PMID 16018821, 2005). "In conclusion, we show that Id4 expression is present primarily in neoplastic astrocytes in both oligodendroglial tumors and GBM, which is in contrast to the expression patterns of Olig1 and Olig2, two survival-associated genes originally identified in GBM tumors." (PMID 16018821, 2005). "An initial report suggested that OLIG1 and OLIG2 might be markers for identification of oligodendroglial tumors." (PMID 16018821, 2005).
optic neuritis (1 paper, 2010). Optic neuritis is inflammation of the optic nerve, the nerve that carries the visual signal from the eye to the brain.The conditionmay cause sudden, reduced vision in the affected eye(s). "Furthermore, Olig1 deficiency attenuated optic neuritis induced by EAE." (PMID 20927333, 2010). "We then investigated the mechanisms leading to the delayed onset of EAE and attenuated optic neuritis in Olig1−/− mice." (PMID 20927333, 2010). "Taken together, these data demonstrate that Olig1 deficiency attenuates both the histological and functional aspects of EAE-induced optic neuritis." (PMID 20927333, 2010). "In the present study, we examined the effect of Olig1 deficiency on EAE and optic neuritis, which is one of the presenting signs of MS." (PMID 20927333, 2010).
periodontitis (1 paper, 2023). An acute or chronic inflammatory process that affects the tissues that surround and support the teeth.
periventricular leukomalacia (1 paper, 2015). Periventricular leukomalacia (PVL) is a brain injury disorder characterized by the death of the white matter of the brain due to softening of the brain tissue. "The aim of this study was to clarify the role of OLIG1 in neonatal Sprague Dawley rats with periventricular leukomalacia (PVL), induced by hypoxia-ischemia (HI)." (PMID 25435330, 2015).
tumor (17 papers, 2005 to 2025). "We found that that 36% (n = 9) of the adenocarcinomas and 59% (n = 20) of the SCCs showed loss of OLIG1 DNA compared to tumor-free lung, and the frequency of deletion was significantly higher in SCCs (p = 0.042, one-tail Z-test)." (PMID 17388669, 2007). "OLIG1 (the gene that encodes a protein involved in nerve cell development) had one of the highest differences in mRNA production between these tumor types." (PMID 17388669, 2007). "Immunohistochemical staining revealed that GFP+ tumor cells in both control and Olig1/2F/+; H2bF/+ groups exhibited robust expression of astrocytic markers, including GFAP and SOX9." (PMID 40428395, 2025). "Our findings not only redefine Olig1/2 as synergistic regulators of astrocytic GBM proliferation but also unveil their conserved roles in cell cycle regulation that is critical for tumor growth." (PMID 40428395, 2025). "Immunohistochemical staining confirmed a complete loss of OLIG1 and OLIG2 protein expression in tdT+ tumor cells of Olig1/2F/+; ISF/+ mice, validating the efficacy of the conditional knockout system in this study." (PMID 40428395, 2025). "Immunohistochemical analysis of tumor tissues in the subventricular zone (SVZ) demonstrated widespread co-expression of OLIG1 and OLIG2 in tdT+ tumor cells." (PMID 40428395, 2025). "The results showed that the number of tumor cells was significantly reduced in Olig1/2 knockout groups compared to controls at both time points." (PMID 40428395, 2025). "The dual-reporter system, in combination with Cre recombinase, enables Olig1/2 knockout in electroporated tumor cells while allowing visualization of the knockout cells and their progeny." (PMID 40428395, 2025). "We first localized the tumor core within the full-brain sagittal sections using the canonical DMG neoplastic cell markers Olig1, Olig2, and Pdgfra." (PMID 40244686, 2025). "Bulk transcriptomic analysis of eGFP+ tumor cells from these mice showed upregulation of specific stem cell markers, including Sox2, Gfap, Olig1, Olig2, Blbp (Fabp7) and Pdgfra31." (PMID 31863004, 2019). "EGFRvIII likely bypasses the proliferative inhibition caused by Olig1/2 loss through constitutive activation of downstream signaling pathways (e.g., PI3K/AKT/mTOR and MAPK/ERK), thereby providing alternative survival and proliferative signals for tumor cells." (PMID 40428395, 2025). "In this study, we hypothesize that Olig1/2 collaboratively drive astrocytic GBM progression by regulating the proliferation of tumor cells." (PMID 40428395, 2025). "Next, to achieve tumor cell-specific knockout of Olig1/2 and enable labeling of the knockout cells, we first crossed Olig1/2F/F mice with two distinct reporter systems: ISF/+ mice (membrane-localized tdTomato labels the cell membrane) and H2bF/+ mice (nuclear-localized GFP marks the nucleus)." (PMID 40428395, 2025). "Interventions targeting a single molecular node (e.g., Olig1/2) may exhibit limited efficacy due to signaling pathway redundancy in tumor cells." (PMID 40428395, 2025). "Notably, although Olig1/2 knockout significantly suppresses tumor proliferation, persistent tumor formation is still detectable in our model." (PMID 40428395, 2025). "Notably, a significant increase in tumor cells was shown in Olig1/2 knockout groups from P20 to P40." (PMID 40428395, 2025). "The tumor tissues displayed an enriched expression of transcription factors (e.g., Dlx2, Gbx2, Foxb1, and Nkx2.2) critical for brain development, tanycyte markers (e.g., Ptprz1, Fabp7, Crym, and Gja1), and differentiation markers (e.g., Dcx, Olig1, and Cspg5)." (PMID 33863883, 2021). "Notably, a significant reduction in GFP+ tumor cells was observed in Olig1/2F/+; H2bF/+ mice." (PMID 40428395, 2025). "Thus, abrogation of OLIG1 protein expression may play a role in inhibiting cellular differentiation, but it could also contribute to the tumor phenotype in other ways through some of its downstream targets." (PMID 17388669, 2007).
tumor (continued). "Given the significant reduction in GFP+ tumor cells in Olig1/2F/+; H2bF/+ mice at P20, we further investigated whether Olig1/2 knockout suppresses tumor initiation by systematically analyzing Olig1/2F/+; H2bF/+ and Olig1/2F/+; ISF/+ mice at a later stage (P40)." (PMID 40428395, 2025). "First, we systematically evaluated the expression profiles of OLIG1 and OLIG2 across major tumor types using the TCGA database." (PMID 40428395, 2025). "The analysis of Olig1/2F/+; ISF/+ tumor-bearing mice at P40 demonstrated significantly reduced tumor sizes compared to controls, while tumor cells maintained high expression of astrocytic markers GFAP and HOPX." (PMID 40428395, 2025). "To quantify the impact of Olig1/2 knockout on tumorigenesis, we examined GFP+ (H2b model) or tdT+ (IS model) tumor cells in the control, Olig1/2F/F; ISF/+, and Olig1/2F/F; H2bF/+ mice at both P20 and P40." (PMID 40428395, 2025). "The present study unveils a critical role for Olig1/2 as synergistic drivers of astrocytic GBM proliferation through direct transcriptional activation of various cyclins, while maintaining tumor cell identity." (PMID 40428395, 2025). "Next, using CRISPR/Cas9 technology to knockout Olig1/2, we found that astrocyte differentiation markers such as GFAP, SOX9, and HOPX were preserved, but tumor cell proliferation was significantly diminished." (PMID 40428395, 2025). "Principal component analysis stratified the tumor types and as expected, IDH1-mutant tumors expressed increased levels of OLIG1 while IDH-wt GBM tumors expressed PDGFA among other stratifying genes." (PMID 38077210, 2023). "We confirmed the restriction of SOX2 expression to tumor cells, PTPRC/CD45 to immune cells, SPI1/PU.1, CD68, and CD163 to ‘macrophages’, CD3G to ‘T cells’, and OLIG1/2 and MBP to oligodendrocytes." (PMID 35973991, 2022). "The genes TNR, OLIG1, and PDGFRA are specific to the OPC cluster and are differentially expressed in tumor and periphery cells." (PMID 35327982, 2022). "CT and PVZ cells expressed neural tumor stem cell markers CD133, NESTIN, OLIG1, OLIG2, SOX2 and A2B5." (PMID 30333910, 2018). "OLIG1 immunohistochemistry was performed on TMA1 comprising 59 adenocarcinomas (Adenos 45–103), 74 SCCs (SCCs 56–129), six tumor-free lung, and four human brain specimens." (PMID 17388669, 2007). "Histological analysis revealed that tumors in Olig1/2F/+; ISF/+ mice at P40 retained the capacity to initiate and migrate, infiltrating adjacent brain regions, albeit with reduced tumor volume, indicating that Olig1/2 knockout does not impair tumor initiation or migratory potential." (PMID 40428395, 2025). "The results showed that no detectable CASPASE-3+ signals in GFP+ tumor cells were observed after Olig1/2 knockout, indicating that the deletion of Olig1/2 did not trigger tumor cell death." (PMID 40428395, 2025). "This indicates that the absence of Olig1/2 leads to a downregulation of MKI67 expression, which means the reduced tumor growth is caused by slowed tumor proliferation." (PMID 40428395, 2025). "Collectively, these findings demonstrate that Olig1/2 knockout does not affect tumor initiation but significantly impedes overall tumor growth." (PMID 40428395, 2025). "Notably, Olig1/2 knockout did not suppress tumor initiation or migration, suggesting that their primary role is to amplify proliferation rather than to drive tumorigenesis." (PMID 40428395, 2025). "Compared to the in vivo situation, we could not identify two clearly distinct SOX9+ and OLIG1+ tumoral cells in these cultures, and the majority of cells coexpressed OLIG1 and SOX9 (Lane 4)." (PMID 33925547, 2021). "In light of these genetic interactions, a growth advantage could be conferred to tumor cells that overexpress SHH through interaction with currently unknown growth promoting targets, while at the same time abrogating OLIG1 expression concomitant to MAG down-regulation." (PMID 17388669, 2007).
tumor (continued). "Whereas neither Nestin-cre::Smarcb1fl/+ nor Olig1-cre::Smarcb1fl/+ mouse strains showed any pathological phenotype (Ca’), hGFAP-cre::Smarcb1fl/+ and Math1-cre::Smarcb1fl/+ mice gave rise to different tumor entities with a tumor penetrance of 11% and 4%, respectively." (PMID 35318328, 2022). "Therefore, this phenotypic difference could stem, in part, from lack or reduced MAG expression in OLIG1 negative tumors, which could facilitate detachment of tumor cells from the primary tumor mass." (PMID 17388669, 2007). "The astrocytic component of OAC may represent a focal area of Id4 expression in tumor subpopulations occurring at later stages after tumor initiation, leading to the co-expression of Id4 with OLIG1 and OLIG2 in neoplastic astrocytes and lack of Id4 expression in neoplastic oligodendrocytes." (PMID 16018821, 2005). "Conversely, GFP+ cells in Olig1/2F/F; H2bF/+ mice showed no co-labeling with OLIG2 or SOX10, confirming that the deletion of Olig1/2 in tumor cells did not alter the astrocytic GBM cell phenotype." (PMID 40428395, 2025). "To investigate if the reduction in tumor cells without Olig1/2 resulted from the altered microenvironment, we investigated the correlation between the expression levels of OLIG1 and OLIG2 and the abundance of six tumor-infiltrating immune cell types in GBM by TIMER." (PMID 40428395, 2025).
cancer (5 papers, 2019 to 2023). A tumor composed of atypical neoplastic, often pleomorphic cells that invade other tissues. "We found that while almost all cancer cells expressed OPC-associated signal transduction factors OLIG1, OLIG2, and PDGFRA, expression of progenitor-associated transcription factors such as SOX2 and SOX10 were highly expressed in cells expressing the MAPK programme." (PMID 31427603, 2019). "Over the past decade extensive studies have established functional roles of Olig1 and Olig2 in development as well as in cancer." (PMID 37274223, 2023). "Overexpression of the other four (SOX2, POU3F2, OCT-4, and OLIG1) or five (SOX2, SALL2, OCT-4, POU3F2, and Bmi-1) transcription factors in YB-1 knockout cancer stem cells generated similar results." (PMID 31375149, 2019). "Furthermore, simultaneous expressions of YB-1 and the other four (SOX2, POU3F2, OCT-4, and OLIG1) or five (SOX2, SALL2, OCT-4, POU3F2, and Bmi-1) transcription factors in YB-1 knockout cancer stem cells restored the stemness of YB-1 knockout cancer stem cells." (PMID 31375149, 2019).
adenocarcinoma (2 papers, 2007 to 2021). A common cancer characterized by the presence of malignant glandular cells. "Immunohistochemical analysis of a large set of adenocarcinomas and SCCs uncovered missing or reduced OLIG1 protein expression in 68% of the specimens tested, suggesting that abrogation of OLIG1 might be of clinical relevance in these subtypes of NSCLC." (PMID 17388669, 2007). "In order to validate our observations, OLIG1 immunohistochemistry was performed on an independent sample set (TMA2), comprising 74 adenocarcinomas (Adenos 104–182) and 79 SCCs (SCCs 130–208)." (PMID 17388669, 2007). "The percentage of samples lacking OLIG1 protein was higher than expected within the adenocarcinoma subgroup." (PMID 17388669, 2007). "This scenario reconciles the initial observations of lower DNA methylation and higher mRNA expression in adenocarcinomas compared to SCCs with the later finding of a higher proportion of OLIG1 negative adenocarcinomas." (PMID 17388669, 2007). "On the basis of the totality of the data collected in this study, it is possible that a post-transcriptional mechanism acting preferentially in the adenocarcinomas may account for either lack of OLIG1 mRNA translation or rapid degradation of the OLIG1 protein product." (PMID 17388669, 2007). "Our analysis determined that 78% (n = 46) of adenocarcinomas and 58% (n = 42) of SCC were either negative or expressed OLIG1 protein at low levels." (PMID 17388669, 2007).
infection (2 papers, 2018 to 2025). The state of being infected such as from the introduction of a foreign agent such as serum, vaccine, antigenic substance or organism. "Moreover, we observed that GZ01 infection also led to the decrease of OPC (Olig1+) and immature oligodendrocytes (CNP+)." (PMID 30083387, 2018). "Conversely, expression levels of ectodermal (Pax6, Gfap, Neurod1, and Olig1) or mesendoderm (Flk1, Eomes, Hnf1b, and Mixl1) markers either not enhanced or only weakly increased after Cre infection." (PMID 40216251, 2025).
neurological diseases (1 paper, 2005). "Both signatures included a number of genes (MBP, MOBP, MAG, OLIG1, and OLIG2) previously found in glial cells, several of which have been linked to neurological diseases." (PMID 16168081, 2005).
psychiatric disorder (1 paper, 2025). A disorder characterized by behavioral and/or psychological abnormalities, often accompanied by physical symptoms. "Concordant with the increased inflammatory signal, there was a downregulation in mRNA expression of genes linked to neurodevelopment and myelination, neurotransmitter regulation, and psychiatric disorders including calcium binding Calb2 and S100b, as well as SNAP25, Pvalb, MAG, Olig1, and Olig2." (PMID 40059770, 2025).
OLIG1 also shares sentences with these, for which no sentence is quoted: CNS tumors (2 papers); melanoma (2); non-small cell lung carcinoma (2); autism (1); brain injury (1); diabetic neuropathy (1); diffuse astrocytoma (1); gastric cancer (1); holoprosencephaly (1); psychosis (1); Stroke (1); viral infection (1).